TNF (tumor necrosis factor)
Diseases named in the same sentence as TNF in open-access papers (continued):
Sharing a sentence is not in itself a finding about the gene and the disease.
atherosclerosis (continued). "Other commercially available agents targeting IL-6 (tocilizumab), TNF-α (etanercept, adalimumab, infliximab), or IL-1 receptor antagonist (anakinra) have mostly been assessed in the setting of other inflammatory diseases and further testing in atherosclerosis is required." (PMID 36555579, 2022). "First, macrophages often infiltrate abdominal adipose tissue, causing increased production of pro-inflammatory cytokines, such as interleukin-6 and tumor necrosis factor-α, which may induce oxidative stress and endothelial dysfunction, ultimately facilitating the development of atherosclerosis." (PMID 36320060, 2022). "KEGG pathway enrichment of DEGs demonstrated that high expression of HMOX1 might have connections with cholesterol metabolism, phagosome, PPAR signaling pathway, TNF signaling pathway, and renin-angiotensin system, most of which were activated through the development of atherosclerosis." (PMID 35498043, 2022). "The beneficial components of ZWD might intervene HF through the AGE-RAGE signalling pathway in diabetic composition, fluid shear stress and atherosclerosis, the TNF signalling pathway, TB, and Kaposi sarcoma related herpesvirus infection, according to a KEGG enrichment study." (PMID 35341142, 2022). "Moreover, the anti-inflammatory effect of adropin can suppress TNFα expression in atherosclerosis." (PMID 35955453, 2022). "Indeed, the positive effects on the endothelium demonstrated in patients treated with TNFα inhibitors suggest that suppression of inflammation itself may prevent atherosclerosis progression." (PMID 36280849, 2022). "Klotho suppressed the expression of TNF α-induced ICAM1 and VCAM1 adhesion molecules and also inhibited TNF- α induced NF-κB activation and IkB phosphorylation—mechanisms involved in inflammation and atherosclerosis, suggesting that Klotho may play a role in mediating endothelial inflammation." (PMID 35055149, 2022). "Atherosclerosis, a chronic inflammatory disease of the arterial wall, has been reported to be associated with various inflammatory cytokines, such as IL-10 and TGF-β, which are associated with Tregs as well as IFN-γ, TNF-α, and IL-17, which are associated with Th1 and Th17 cells." (PMID 36405994, 2022). "To summarise, our study indicates that the use of TNFα inhibitors may have a protective effect against subclinical atherosclerosis in patients with RA, given that patients on this biologic have a smaller CIMT than patients on other disease-modifying antirheumatic drugs." (PMID 35054229, 2021). "Thus, TNF-α may play an important role in vascular disease, confirming a pivotal role of this pro-inflammatory cytokine in the pathogenesis of atherosclerosis, endothelial damage and heart-cell remodelling toward higher disease severity." (PMID 35053192, 2021). "Thus, it could be hypothesized that the systemic proinflammatory status contributes to atherosclerosis in vitiligo patients and the crucial role might be played by the key cytokines in vitiligo pathogenesis, such as IL-1, IL-6, TNF-α, and possibly IL-17." (PMID 34445526, 2021). "However, inflammatory cytokines TNF-α, IL-1β, and IL-6 are important in atherosclerosis pathogenesis, as recently shown by the CANTOS trial, which found that specifically targeting inflammation (IL-1β inhibition) improves clinical outcomes in patients with a previous myocardial infarction." (PMID 32647892, 2021). "Interestingly, injection of TNFα-deficient B2 cells failed to increase atherosclerosis in B cell-deficient or lymphocyte-deficient Rag2−/−Apoe−/− mice, whereas WT B2 aggravated plaque size by 80%." (PMID 33572939, 2021).
atherosclerosis (continued). "Moreover, PD-1 expressing CD8+ T cells from patients with atherosclerosis produced more anti-atherogenic IL-10 and less pro-atherogenic cytokines (IFNγ, TNFα) compared to PD-1−CD8+ T cells, further supporting a protective role for PD-1 in T cell-mediated immunity." (PMID 34790707, 2021). "It has been shown that specific therapies targeting the pro/anti-inflammatory cytokines such as CCL2, TNFα, and IL-6 have suggested slowing in the progression of atherosclerosis in animal models and might improve cardiovascular outcomes in human subjects in large-scale phase III trials." (PMID 32821283, 2020). "The chronic inflammation is also a well-defined nontraditional CVD risk in the pathogenesis of atherosclerosis, where cytokines including IL-1, IL-6 and TNF-α could promote endothelial dysfunction, a key process in atherogenesis." (PMID 32665015, 2020). "Furthermore, miR-146a treatment in vitro may induce the expression by these cells of key inflammatory cytokines/transcription factors involved in atherosclerosis (i.e., TNFα, MCP-1 and NFκB)." (PMID 32188016, 2020). "Granzyme B and perforin release by the activated T cells could also contribute to endothelial cell damage and death–indeed, in an adoptive transfer mouse model of atherosclerosis, transfer of CD8 T cells deficient in granzyme B, perforin, or TNF attenuated atherosclerotic lesions." (PMID 32976527, 2020). "Given that atherosclerosis is an inflammatory disease promoted by specific cytokines, such as interleukin (IL)-1β, IL-6, and tumor necrosis factor (TNF)-α, we aimed at evaluating whether sex could affect the levels of these proatherogenic cytokines in a group of healthy adults." (PMID 32485823, 2020). "Thus, we have identified a possible feed-forward model of atherosclerosis in which plaque-infiltrating CX3CR1+ CD8 T cells are exposed to vascular EC-derived IL-15 that induces antigen-independent TNF release, resulting in enhanced release of CX3CL1 and IL-15 from ECs." (PMID 32976527, 2020). "L5 may contribute to atherosclerosis by augmenting macrophage foam cell formation, upregulating CD11c expression, or enhancing the expression of inflammatory mediators, such as IL-6, IL-8, and TNF-α." (PMID 32824307, 2020). "Since it has been speculated that RA-related inflammation might contribute to endothelial dysfunction, anti-TNF therapy has been shown to improve vascular function, which strongly indicates involvement of systemic inflammation in the development of premature atherosclerosis." (PMID 32351667, 2020). "Meanwhile, growing evidences have confirmed that, some inflammatory cytokines, such as IL-10, IL-1β, IFN-γ and TNF-α, may be responsible for the pathogenesis of atherosclerosis because these cytokines can result in the adhesion of leukocytes to vascular endothelium and foam cell formation." (PMID 32169038, 2020). "Besides, KEGG results also suggested that XFZYD might reduce the inflammatory response in atherosclerosis principally by affecting TNF signaling pathway and Toll-like receptor (TLR) signaling pathway." (PMID 33425996, 2020). "Our findings suggest that TNF-α plays a central role as an inflammatory marker of atherosclerosis, and predicts CV events in healthy subjects, whereas long-term TNF inhibition improves LV longitudinal and radial systolic deformation, which may even normalize during the course of treatment." (PMID 31285841, 2019). "In addition to antigen presentation to CD4 T cell, B cells can potentially aggravate atherosclerosis by at least two other mechanisms, namely the production of atherogenic IgG and the secretion of pro-inflammatory cytokines, including TNFα, which are T cell-independent pathways." (PMID 31206525, 2019). "CD4+ T cell exosomes can induce TNF-α in monocytes, which may contribute to atherosclerosis." (PMID 31615107, 2019).
atherosclerosis (continued). "Increased levels of pro-inflammatory cytokines [such as tumor necrosis factor alpha (TNFα), interleukin-8 (IL-8), and monocyte chemoattractant protein-1 (MCP-1)], adipokines, and autoantibodies are associated with the progression of endothelial dysfunction toward atherosclerosis development." (PMID 28167944, 2017). "In addition, PI-PLCγ1, activated by TLR4 stimulation with minimally oxidized LDL, induces ROS generation in macrophages, leading to the production of pro-inflammatory cytokines such as TNF-α, IL-1β and IL-6, all having central roles in the pathogenesis of atherosclerosis." (PMID 28661459, 2017). "Furthermore, inhibition of TNF-α reduces atherosclerosis in apolipoprotein E knockout mice." (PMID 28427397, 2017). "Conversely, TNFα-induced atherosclerosis could also be enhanced by activating TAK1." (PMID 29029426, 2017). "Additionally, pre-clinical and clinical evidence support the role of TNF-α in atherosclerosis." (PMID 28706194, 2017). "Some evidence point to a beneficial effect of anti-TNF-α agents on vascular wall physiology raising the possibility that TNF-α blockade may improve endothelial function in RA patients with consequently reduced progression of subclinical atherosclerosis and improvement of arterial stiffness." (PMID 28706194, 2017). "Nevertheless, resistin has primarily been shown to be relevant to inflammation-related diseases like atherosclerosis and arthritis and may have a role in the regulation of pro-inflammatory cytokines’ (IL-6 and TNF-α) expression in human peripheral blood mononuclear cells (PBMC) via NF-κB pathway." (PMID 27608037, 2016). "However, little is known if pharmacological TNF-α inhibitors could be successfully used to limit progression of atherosclerosis in experimental models." (PMID 27467817, 2016). "Therefore, the down-regulation of miR-146a may increase inflammation-related atherosclerosis and affect vascular damage response by increasing the levels of TNF-α, TRAF6, and IRAK1." (PMID 27164084, 2016). "In addition to cholesterol and fat accumulation, macrophages serve as important regulators of inflammation in atherosclerosis development; while β-carotene induced changes in the inflammatory response in the Raw264.7 macrophage cell line and a reduction in IL-6 and TNF-α secretion to the medium." (PMID 25629601, 2015). "Ceramide-loaded LDL has been shown to stimulate TNF-α and IL-6 production in cultured macrophages through NF-κB activation suggesting that ceramide-induced cytokine production in the circulation can target endothelial cells, which would exacerbate atherosclerosis through inflammatory mechanisms." (PMID 25993337, 2015). "Interestingly, Zhang and colleagues demonstrated that TNFα is capable to induce transcytosis of LDL at the first stages of atherosclerosis development through a mechanism dependent of nuclear factor kappa B (NF-κB) and peroxisome proliferator-activated receptor gamma (PPAR-γ) crosstalk." (PMID 26578976, 2015). "Activation of endothelial cells by proinflammatory molecules, including tumor necrosis factor α (TNFα), increases the expression of adhesion molecules and the adhesion of leukocytes to the vascular endothelium, which are critical steps in the initiation of atherosclerosis." (PMID 24517399, 2014). "TNF-α and IL-6 have been reported to be significantly associated with the severity of subclinical atherosclerosis, independent of Framingham risk score in RA, and IL-6 was recently also documented to be very strongly and independently associated with surrogate markers of early atherogenesis in RA." (PMID 25514790, 2014). "Furthermore, it is believed that decreased expression of CD36 in macrophages, induced by various cytokines, is linked to the development of atherosclerosis, possibly due to Toll-like receptor (TLR) pathway activation arising from the increase in cytokines, such as TNF-α." (PMID 24349333, 2013). "Therefore, hVSMCs and TNF-α decisively promote atherosclerosis and inflammation." (PMID 23651618, 2013).
atherosclerosis (continued). "Traditional cardiovascular risk factors and inflammatory markers (hsCRP, IL-6, TNFα, adiponectin) were studied together with IMT (intima-media thickness), FMD (flow mediated dilation), and LVMi (left ventricle mass index) as surrogate markers of subclinical atherosclerosis." (PMID 23554546, 2013). "Adipose tissue secretes a number of bioactive molecules, such as resistin, TNF-α, and IL-6 collectively called adipokines, which affect peripheral insulin sensitivity and may be important players in the development of type 2 diabetes and atherosclerosis." (PMID 23484124, 2013). "By virtue of its strong correlation to plasma TNF-alpha, F2R may be an important mediator of the effects of inflammation on the vessel wall, and this study further provided promising strategies of blocking F2R to the treatment of human atherosclerosis." (PMID 22761820, 2012). "Rg1 has been reported to inhibit TNF-α-induced human arterial smooth muscle-cell proliferation and cause cell-cycle arrest in G1 phase, and PDGF-BB is known to be a mitogen involved in the development of vascular proliferative lesions observed in atherosclerosis and in restenosis after angioplasty." (PMID 22474498, 2012). "Since inflammation plays a central role in the pathogenesis of atherosclerosis and its complications, a number of studies have investigated the association between smoking and increase in several inflammatory markers, such as CRP, interleukin (IL)-6, tumor necrosis factor (TNF)-α, and CD40L." (PMID 22577249, 2012). "Taken together, these data imply that particular treatment modalities that induce disease remission, such as corticosteroids and TNF inhibitors, may be very important or even more important than disease remission per se as far as the subclinical atherosclerosis in RA is concerned." (PMID 22390577, 2012). "Recently, a significant role in the regulation of the immune response accompanying atherosclerosis has been ascribed to interactions between activated T cells, promoting the expression of systemic inflammatory response factors participating in atherogenesis, such as TNF–α and IL-6." (PMID 22558213, 2012). "In addition to their anti-inflammatory effect, which seems beneficial in atherosclerosis, anti-TNFα agents could correct endothelial dysfunction and lipid profile abnormalities reported in chronic inflammatory diseases." (PMID 17335569, 2007). "Seven core targets-IFNG, CXCL8, TNF, TGFB1, IL2, IL4, and RELA-were identified via network pharmacology, involving key pathways such as lipid-atherosclerosis, AGE-RAGE, and IL-17 signaling." (PMID 40708520, 2026). "Increases SOD and GSH in serum in diseased mice.Suppresses the expression of IL-6, TNF-α, ICAM-1, VCAM-1 and NLRP3.Ameliorates atherosclerosis." (PMID 41300435, 2025). "Studies have demonstrated that in patients with atherosclerosis, Lcn2 can also be synthesized by TNF-α-stimulated macrophages, thereby enhancing the mRNA expression of M1 macrophage markers including TNF-α, iNOS, IL-6, and CCL5." (PMID 39180285, 2025). "By impeding the movement of monocytes into the vascular endothelium triggered by TNF‐α, ALE showcased its ability to thwart the initial stages of atherosclerosis." (PMID 40161001, 2025). "Red watermelon has potential in atherosclerosis prevention by modulating the expression of PCSK9, LOX-1, CD36, ROS, TNFα, and ABCA1." (PMID 40699832, 2025). "Curcumin also decreases the expression of pro‐inflammatory adipokines such as TNF, MCP‐1, and plasminogen activator inhibitor‐1 (PAI‐1), while inducing the expression of lipocalin, which can inhibit the progression of atherosclerosis." (PMID 40634132, 2025). "The most notable pathways included lipid and atherosclerosis, adipocytokine signaling, PI3K-Akt signaling, NF-kappa B signaling, IL-17 signaling, TNF signaling, platelet activation, and regulation of lipolysis in adipocytes." (PMID 41011287, 2025).
atherosclerosis (continued). "This study aimed to explore the effects of red watermelon extract on the expression of PCSK9, LOX-1, ROS, TNFα, CD36, and ABCA1 in a Wistar rat model of atherosclerosis." (PMID 40699832, 2025). "Inflammatory mediators, such as tumor necrosis factor-alpha (TNF-α), can further exacerbate endothelial dysfunction and contribute to the development of atherosclerosis." (PMID 39941147, 2025). "Chronic inflammation is also a well-defined non-traditional risk factor in the pathogenesis of atherosclerosis, where cytokines such as interleukin 1 (IL-1), interleukin 6 (IL-6), and TNF-α may promote endothelial dysfunction, which plays a key role in the process of atherogenesis." (PMID 41301765, 2025). "KEGG pathway enrichment analysis showed 182 signaling pathways, including the PI3K-Akt, TNF, IL17, apoptosis, NAFLD, and lipid and atherosclerosis signaling pathways." (PMID 40166691, 2025). "Like mir-126, mir-155 serves as a trigger for atherosclerosis, as its activation through inflammatory cytokines such as IFN-β and IFN-γ via TNF-α upregulates macrophage stimulation." (PMID 39941130, 2025). "While earlier works emphasized well-known inflammatory markers (e.g., IL6, TNF-α), we identified novel candidates (OAS2, TMEM106A, ABCB1) with limited prior links to atherosclerosis or stroke." (PMID 40371070, 2025). "The top 20 signaling pathways were mainly enriched in the lipid and atherosclerosis pathways, the AGE-RAGE signaling pathway in diabetic complications, the HIF-1 signaling pathway, the TNF signaling pathway, etc.." (PMID 40909020, 2025). "Consistently, Zhao and colleagues have demonstrated that SAB reverses atherosclerosis and inflammation by suppressing nuclear translocation of NF-κB and NLRP3 inflammasome activation in TNF-α-treated human umbilical vein endothelial cells." (PMID 40722987, 2025). "Top enriched pathways included those related to atherosclerosis and shear stress, AGE-RAGE signaling, lipid and atherosclerosis, TNF signaling, and chemokine signaling." (PMID 41465425, 2025). "Ginger has been shown to inhibit the expression of pro-inflammatory mediators, such as TNF-α, IL-1β, and monocyte MCP-1, which play crucial roles in the development and progression of atherosclerosis." (PMID 39941147, 2025). "Pro-inflammatory mediators (IL6, TNF-α, and CRP) driven by periodontal disease are also known promoters of endothelial dysfunction, atherosclerosis, and destabilization of atherosclerotic plaque." (PMID 41011105, 2025). "In animal models of atherosclerosis, DPP-4is lower circulating CRP, MCP-1, IL-6, and TNF-α while raising the anti-inflammatory IL-10." (PMID 41462689, 2025). "Cytokines like TNF-alpha, IL-6, and CRP are chronically elevated, contributing to endothelial dysfunction and promoting atherosclerosis, a primary driver of ischemic stroke." (PMID 40125129, 2025). "Potential pathways were also predicted, including those involved in lipid metabolism, atherosclerosis, PI3K‐Akt signaling, MAPK, IL‐17, TNF, neurotrophin signaling, apoptosis, Alzheimer's disease, and other neurodegenerative diseases." (PMID 40994138, 2025). "These agents also suppress inflammatory pathways by reducing pro-inflammatory cytokines such as interleukin-6 (IL-6) and tumor necrosis factor-alpha (TNF-α), thus stabilizing atherosclerotic plaques and slowing atherosclerosis progression." (PMID 40807170, 2025). "This study was conducted to explore how red watermelon (Citrullus lanatus) consumption modulates the lipid profile, and the expression of PCSK9, LOX-1, CD36, ROS, TNFα, and ABCA1 so that it can inhibit the development of atherosclerosis." (PMID 40699832, 2025). "Fluid shear stress and atherosclerosis, AGE-RAGE signaothelial migration, and TNF signaling pathway." (PMID 41009970, 2025).